GSK3B (glycogen synthase kinase 3 beta)
Diseases named in the same sentence as GSK3B in open-access papers (continued):
Sharing a sentence is not in itself a finding about the gene and the disease.
tumor (continued). "GSK3β takes part in decreasing matrix-metalloproteinase expression and is therefore thought to maintain a stem cell phenotype in tumor cells, but without diminishing their metastatic potential." (PMID 32767962, 2021). "Furthermore, PBMF treatment notably upregulated the mRNA expression levels of GSK-3β, E-cadherin, Bax, Caspase-3, and Caspase-9 but substantially downregulated those of β-catenin, N-cadherin, MMP-2, MMP-9, Snail, and Cyclin D1 in tumor tissues." (PMID 33964908, 2021). "Their tumor-suppressive activity on A2780 and OVCA433 lines differed depending on the numbers of carbon atoms in their structures, the compound named 20 g being most specific towards GSK3β and most effective in suppressing malignant cell growth." (PMID 32767962, 2021). "As expected, administration of simmiparib significantly inhibited the growth of GSK3β KO tumor xenografts, but not the parental tumor xenografts." (PMID 33589588, 2021). "Gsk3b−/− mice suppressed tumor growth to the same degree as Gsk3a/b−/− mice, whereas Gsk3a−/− mice behaved similarly to wild-type, revealing an important role for GSK-3β in regulating T cell-mediated anti-tumor immunity." (PMID 34142056, 2021). "Similar to tumor rejection, depletion of Gsk3a alone, unlike Gsk3b, has no direct effect on PD-1 expression, whereas depletion of both together caused the effect to be magnified." (PMID 34142056, 2021). "For furthermore analysis, we utilized The Cancer Genome Atlas (TCGA) public database and identified GSK3β, β-Catenin, STAT3, and CD44 oncogenes to be overexpressed in GBM tumor samples compared to adjacent normal tissue groups, and this was associated with poor cancer prognoses." (PMID 33671112, 2021). "DCBLD2 stabilizes β-catenin by phosphorylating GSK3β and transporting accumulated β-catenin to the nucleus to promote the expression of EMT-related transcriptional factors (TFs), ultimately resulting in tumor metastasis." (PMID 33808696, 2021). "In contrast mutant KRas-independent tumors do not require GSK-3β for viability, survival, and tumor growth." (PMID 34955846, 2021). "Additional studies have shown that GSK-3β may exert positive effects on cell proliferation and the GSK-3β protein is overexpressed in certain tumor types, including colon, liver, ovarian, and pancreatic cells." (PMID 33917370, 2021). "Here, we demonstrate that GSK-3α rather than GSK-3β is the primary isoform restraining the expression of NKG2D ligands, particularly ULBP2/5/6, on tumor cells, thereby regulating their susceptibility to NK cells." (PMID 33918810, 2021). "In these studies, the decrease in Hes-1 expression by presenilin blockage resulted in PTEN and GSK-3β activation, whereas inhibiting either PTEN or GSK-3β activation increases Hes-1 expression which counteracts their effects on inhibiting tumour cell proliferation." (PMID 34671031, 2021). "In addition, we also investigated the expression of the Akt/GSK-3β/Snail axis and EMT correlated proteins in HCC tumor tissues using western blotting and IHC analyses." (PMID 33762939, 2021). "However, miR‐125b acts as a tumour suppressor in human papillomavirus (HPV) E6‐infected oesophageal cancer, as its overexpression reverses the down‐regulation of the tumour suppressor GSK3β in the H6‐up‐regulated Wnt signalling pathway." (PMID 33332677, 2021). "SNAI2 is upstream target of GSK-3β/β-catenin, and SNAI2 upregulation could promote the activation of GSK-3β/β-catenin to mediate the invasion and migration of some tumor cells." (PMID 34966442, 2021). "Overexpression of GSK-3β confers HCC cell colony formation and xenograft tumor growth." (PMID 31938062, 2020). "During tumor growth, STIM1 stabilized Snail1 protein by activating the CaMKII/AKT/GSK-3β pathway." (PMID 32483465, 2020). "Using anti-phosphor-Ser/Thr (p-S/T) antibody, we confirmed that GSK-3β could induce RXRα phosphorylation in HepG2 cells and HCC tumor tissues." (PMID 31938062, 2020).
tumor (continued). "According to recent studies and results from our laboratory, the anti‐tumour effect of 20(S)‐PPD was mainly induced by apoptosis through inhibiting Akt phosphorylation, including reducing the expression of phosphorylated GSK3β, which promoted β‐catenin accumulation and intestinal tumorigenesis." (PMID 33128348, 2020). "The interrelationship between GSK-3β/β-catenin has been described in the development of multidrug resistance in CCA and it is shown that Wnt3a activates GSK-3β/β-catenin signaling to up-regulate the expression of P-glycoprotein efflux pump on the tumor cells." (PMID 32140709, 2020). "Inactivation of GSK-3β phosphorylation facilitates the nuclear localization of β-catenin, leading to the activation of GSK/β-catenin signaling pathway, increasing the expression of snail, ZEB1 and Twist, thereby promoting tumor EMT and metastasis." (PMID 33192529, 2020). "We noted that high GSK-3β was not correlated to downregulation of total and nuclear β-catenin, suggesting that the tumor-suppressing effect of GSK-3β via Wnt/β-catenin was lost in HCC." (PMID 31938062, 2020). "Studies have shown that metformin inhibits the invasion and metastasis of tumor cells and induces degradation of cyclin D1 through AMP-activated protein kinase/glycogen synthase kinase 3 beta (AMPK/GSK3β) signaling axis to participate in the protein ubiquitination process." (PMID 32631421, 2020). "This conclusion is further supported by analyses of the expression of GAD1, GSK3β, PKM2, and CPT1 in cervical lesions, and the results of these analyses imply that enhanced aerobic glycolysis and disturbed lipid metabolism are advantageous to tumor growth." (PMID 31465717, 2020). "The results showed that GSK3β and GAD1 were significantly downregulated and CPT1A and PKM2 were upregulated in CSCC compared with NC samples (p < 0.05), indicating that the catabolism of sugar and lipids was enhanced in tumor cells." (PMID 31465717, 2020). "In tumor cells, AKT can be transformed into pAKT through phosphatidylinositol 3-kinase phosphorylation, and pAKT can promote cell proliferation and inhibit cell apoptosis by activating caspase 9, Bad, FOXO, GSK-3β and IKK by phosphorylation." (PMID 33221748, 2020). "Our studies demonstrated that SDF-1 and HGF, which may stimulate tumor cells to form metastases, increase the SNAIL level by inducing GSK3β phosphorylation via the PI3K-AKT pathway." (PMID 32664538, 2020). "In the absence of WNT ligands, GSK3β mediates the phosphorylation-dependent proteasomal degradation of PD-L1 by β-TrCP, and tumor infiltration is ultimately increased by interferon-producing CTLs." (PMID 31616443, 2019). "Although not in inflammation, GSK3B has been previously reported to interact with miRNAs in neoplasia and several types of cancer." (PMID 31801236, 2019). "Altogether, our data indicate that co-blockade of GSK3β and Chk1 significantly inhibits TNBC growth in vitro in both 2D and 3D cultures and suggest that in some tumours the double therapy could be effective." (PMID 31362447, 2019). "During the course of analysis of the role of estrogen in activating EMT, we observed that E2 stimulated expression of p-Akt, p-Gsk3β, and p-4Ebp1, downstream targets of Akt, in p18−/−;Brca1MGKO tumor cells, which was not blocked by 4OHT." (PMID 29996906, 2018). "We treated p18−/−;Brca1MGKO and SUM149 tumor cells with or without E2 and found that E2 stimulated expression of p-Akt, p-4Ebp1, p-mTor, and p-Gsk3β in all time points tested from 2 to 144 h." (PMID 29996906, 2018). "Therefore, investigation of the effects of GSK3β inhibition on primary CRC cells (e.g. primary cultures of tumors from CRC patients and patient-derived tumor xenografts) will facilitate therapeutic application in CRC patients." (PMID 29568361, 2018). "While Western blot results did not detect significant change of p-STAT5a and p-GSK3β expression in the tumor tissues from KD group when compared to NC group (p > 0.001)." (PMID 29416654, 2018).
tumor (continued). "Western blot analysis conducted on excised tumor tissue from treated animals revealed that treatment with hirsutine resulted in cleavage/activation of ROCK1, activation of PTEN, inactivation of PI3K, Akt and dephosphorylation of GSK3β." (PMID 29789524, 2018). "Along these lines, because GSK3β-mediated phosphorylation is required for degradation of c-Myc, cyclin E and MCL1, any signaling pathway that affects GSK3β activity can have a profound impact on FBXW7’s ability to perform its tumor suppressor activities." (PMID 30086763, 2018). "Daily repeated treatment with NYT for 14 days did not affect the expression of phosphorylated Akt and GSK3β in the gastrocnemius muscle of tumor-bearing mice." (PMID 30555329, 2018). "GSK-3β, a serine/threonine kinase, is abnormally enriched in human PC cells and another downstream effector of AKT and can be phosphorylated and deactivated by AKT, its aggregation in the nucleus is related to tumor differentiation and kinase activity." (PMID 30670971, 2018). "Consequently, we combined IL-6 with growth-induced stress for tumor cells and found that solid stress enhanced EMT and stem-like properties induced by IL-6 in ccRCC via the Akt/GSK-3β/β-catenin signaling pathway." (PMID 28846080, 2017). "Therefore, Vimentin appears to be a general target during GSK-3β inhibition, implying that GSK-3β participates in the protection of mesenchymal characteristics in tumor cells." (PMID 28821798, 2017). "In the following, we further tested the reverse expression relationship between miR-410 and Gsk3β, as well as their correlation with clinicopathological characteristics (metastasis and differentiation) in 36 pairs of human NSCLC tumor tissues and adjacent normal tissues." (PMID 28076327, 2017). "Since GSK3β induces phosphorylation and degradation of its downstream targets, and some GSK3β substrates are key proteins for promoting cell survival, such as β-Catenin, Cyclin D1, eIF2B and MYC, it was initially considered as a tumor suppressor." (PMID 28800359, 2017). "Similar to TNF-α, IL-β from macrophages could also induce phosphorylation of GSK3β, stabilize β-CATENIN, and thereby increase the expression of Wnt pathway downstream target genes in tumor cells." (PMID 28402277, 2017). "Alcohol may initially activate EGFR/ErbB2 and/or induce ROS, which stimulate critical signaling components, such as p38 MAPK, Wnt/GSK3β/β-catenin, and TLR4/Nanog, as well as alter tumor microenvironment, resulting in the promotion of CSCs." (PMID 29156633, 2017). "In conclusion, the up-regulation of sCLU expression at early staging of HCC is considered to promote tumor development and exacerbate the survival of HCC patients, which may be related to the phosphorylation of AKT/GSK-3β." (PMID 28881732, 2017). "AKT2 represses GSK3β activity by increasing the phosphorylation level of GSK3β protein at Ser9 residues, and has been reported to be upregulated in CRC tissues compared to normal colon mucosa and promote tumor progression." (PMID 29258530, 2017). "Furthermore, we also revealed that CXCL5 secreted by tumor cells was able to promote CRC migration through ERK/Elk-1/Snail-mediated EMT (Epithelial mesenchymal transition) and invasion via the AKT/GSK3β/β-catenin/MMP7 pathway in a CXCR2-dependent manner." (PMID 28356111, 2017). "Among these genes, many are involved in tumour suppression [e.g. RB1], apoptosis [e.g. BCL2L1], the cell cycle [e.g. CCND1, CCND2] or protein kinases [e.g. KIT, GSK3‐β]." (PMID 28539478, 2017). "Also, other studies with GSK-3β inhibitors on GBM patients and two established cell lines (U251 and U87-MG) showed that inhibition of GSK-3β phosphorylation significantly reduced tumor invasiveness." (PMID 27123999, 2016). "NK cells lacking GSK3β exhibited 30–40% tumour cell killing compared with 10–15% killing by wild-type NK cells." (PMID 27040177, 2016).
tumor (continued). "Therefore, DDX3-induced tumor invasion due to increasing β-catenin expression by its protein phosphorylation and stability via the KRAS/ERK/PTEN/AKT/GSK3β cascade." (PMID 27007150, 2016). "We have previously shown that acute proteasome inhibition produced a consistent and dose dependent inhibition of the GSK-3β protein in the tumor cell line MCF7 but not in the normal mammary cell line MCF10A24." (PMID 25941117, 2015). "This indicated that MAP3K3 knockdown suppressing tumor cell growth and invasion may through regulate AKT and GSK-3β pathways." (PMID 26088427, 2015). "Silencing of GSK3α, but not GSK3β resulted in reduced proliferation and enhanced apoptosis in tumor xenografts." (PMID 25714023, 2015). "The results showed that the levels of FAK, PYK2, GSK3β, p-GSK3α/βY279/Y216 and β-catenin were all significantly elevated in tumor tissues, with more than 1 score point difference between normal and tumor tissue on average." (PMID 26274564, 2015). "Furthermore, knockdown of GSK3β in NSCLC cell lines suppressed cell proliferation, arrested tumor cells in G0/G1 phase, induced apoptosis and reduced cell motility." (PMID 24618715, 2014). "Our data indicate that increased Wnt signaling is not mechanistically involved in the observed anti-tumor effects mediated by pharmacologic GSK-3β inhibition." (PMID 25344861, 2014). "These observed anti-tumor effects appear to be largely Wnt-independent as simultaneous Wnt inhibition does not reverse the observed antitumor effects of GSK-3β blockage." (PMID 25344861, 2014). "GSK3β was prominently expressed in NSCLC (n = 211), primarily in the cytoplasm of tumor cells." (PMID 24618715, 2014). "Western blot analysis of tumor xenografts showed that wortmannin treatment resulted in inactivation of PI3K/AKT pathway and induction of apoptosis, as indicated by the decreased expression levels of p-AKT and p-GSK3β, as well as increased cleaved caspase-3." (PMID 25344912, 2014). "Our findings indicate that GSK3β inactivation may account for EZH2 overexpression and subsequent tumour progression, and this mechanism might be a potential target for NPC therapy." (PMID 23874688, 2013). "In AR-A014418-treated mice, Y216-phosphorylation of GSK3β appeared to decrease in the tumors, and membranous expression, but no nuclear accumulation of β-catenin was observed in tumor cells." (PMID 23408967, 2013). "Several studies have suggested opposite roles for GSK3β in the same cellular events mediated by the protooncoproteins and tumor suppressors between non-neoplastic and cancer cells." (PMID 23408967, 2013). "Moreover, we determined the effect of inhibition of GSK3β activity on EZH2 expression and tumor invasiveness in NPC cell lines in vitro." (PMID 23874688, 2013). "As compared to the results for the 80 kDa PRLr product the 2 tumours with barely detectable Ser9-phosphorylated GSK3β lacked the PRLr 80 kDa product." (PMID 22606260, 2012). "Thus SELN6.0, similarly to exosomes from SOJ-6 tumor cells decreased the phosphorylation of PTEN and of GSK-3β leading to functional proteins and drove SOJ-6 cells to the mitochondrial-dependent apoptotic pathway." (PMID 23094054, 2012). "Out of the 6 tumours with weak Ser9-phosphorylated GSK3β,3 lacked and one had weak PRLr 80 kDa expression." (PMID 22606260, 2012). "GSK3β phosphorylation for some nuclear transcription factors, such as β-catenin and Snail, trigger proteasomal degradation, following with suppression on epithelial–mesenchymal transition (EMT) and tumor invasion." (PMID 22363707, 2012).
tumor (continued). "The results of the differential expression analysis of the pre- and post-therapeutic tumour specimen also suggests that the impact of GSK3B and CTNNB1 to this signature is not dependent on chemotherapy but rather related to a property of the primary tumour." (PMID 22970250, 2012). "To determine whether inhibition of GSK-3β has an effect on tumour growth in vivo, we implanted MT450 cells into syngeneic rats and examined the effect of LiCl on the outgrowth of the ensuing tumours." (PMID 21609428, 2011). "Furthermore, co-transfection of BRG1 siRNA and p-Akt1 restored cell growth accompanied by upregulation of p-Akt, p-GSK-3β and cyclin D1 levels, whereas transduction of PTEN siRNA decreased tumour-suppressing effect of BRG1 silencing." (PMID 21102582, 2011). "Interestingly, ex vivo cells from primary tumor biopsies allowed the identification of a CD133- subpopulation of cells that express stem cell markers and are depleted by inactivation of GSK3β." (PMID 19823589, 2009). "Especially, the phosphorylation of GSK3β, the downstream target of the active AKT, could promote the nuclear accumulation of β-catenin, thereby regulating cell apoptosis, stemness, fibrosis, and tumor angiogenesis." (PMID 41369408, 2025). "All in, PRMT5 interacts with CD38 activating the phosphorylation of GSK3β through the ADO-cAMP-PKA axis, augmenting stabilization of PD-L1 expression and subsequently inhibiting CD8+ T cell-mediated tumor cell killing, supporting tumor cells to evade immune surveillance." (PMID 40701777, 2025). "This implies that GSK-3β inhibitors could potentially exert a therapeutically negative, pro-survival effect on tumor cells." (PMID 40157890, 2025). "Further studies revealed that D-mannose inactivates GSK3β, enhances the nuclear translocation of TFE3, upregulates the transcription levels of lysosomal biogenesis-related genes, and promotes lysosomal-mediated degradation of VEGFR2, thereby inhibiting angiogenesis and tumor growth in CRC." (PMID 40259886, 2025). "Notably, although individual deletion of GSK3α or GSK3β upregulates β-catenin, neither manipulation induces tumor or polyp formation." (PMID 41300341, 2025). "However, the regulation of GSK3b/p65, DSB repair and other signaling pathways by KMT2C needs to be further investigated, and the specific mechanism of KMT2C’s action in other tumors and its potential as a novel anti-tumor therapy need to be further studied." (PMID 39165358, 2024). "However, no direct evidence supports the tumor-suppressor role of this kinase, nor the effect of GSK3β inhibition on promoting cancer development and progression." (PMID 38318525, 2024). "Moreover, CH has shown to inhibit hypoxia-driven progression of vasculogenic mimicry during angiogenesis, which is a common characteristic feature observed in tumour microenvironments by reducing the expression of HIF-1α, SPHK-1 and phospho-Akt/GSK-3β signaling in cancer cells." (PMID 38966181, 2024). "Metavert is a dual inhibitor that was developed to inhibit GSK3-β driven tumor-promotion via NF-κB activation, as well as blocking histone deacetylase (HDAC) classes to interfere with epithelial to mesenchymal transition (EMT), which otherwise would be enhanced by GSK3-β inhibition." (PMID 39217851, 2024). "In these studies, suggest that miR-224-5p plays a significant role in the occurrence in HCC samples compared to adjacent tumor tissue samples, which is consistent with our findings that miR-224-5P was four times more abundant in HCC tissues with highly represented BCL2, MTOR, and GSK3B genes." (PMID 37168369, 2023).